TWIST1 (twist family bHLH transcription factor 1)
Diseases named in the same sentence as TWIST1 in open-access papers (continued):
Sharing a sentence is not in itself a finding about the gene and the disease.
craniosynostosis (continued). "The role of cWnt signaling on skeletal stem/progenitor cell expansion and craniosynostosis was further investigated by cross-breeding a Twist1+/− mouse harboring COR craniosynostosis with an Axin2LacZ/+ mouse, endowed with endogenous activation of cWnt signaling." (PMID 34330896, 2021). "Ensuing screening of the Twist1+/−:Axin2lacZ/+ double transgenic COR sutures for complete unilateral or bilateral craniosynostosis revealed a frequency of 0% in wild-type mice, as expected; 83% in Twist1+/− mice; and 0% in Twist1+/−:Axin2lacZ/+ double transgenic mice." (PMID 34330896, 2021). "To test this hypothesis, we surgically ablated the synostotic COR suture of Twist1+/− mice via suturectomy, reflecting the surgical management of human craniosynostosis." (PMID 34330896, 2021). "Thus, the goal of this study was to describe the major clinical features associated with craniosynostosis, as well as to identify the frequency of pathogenic variants in FGFR1, FGFR2, FGFR3, and TWIST1 in a sample of Mexican patients." (PMID 32510873, 2020). "While our data suggest that dysregulation of the TWIST1/RUNX2 and IGF1/Akt pathways may predispose humans to craniosynostosis, further translational research is necessary before the development of clinical utility." (PMID 31442251, 2019). "However, other researchers found that Twist1 heterozygous mice survived until adulthood and exhibited calvarial phenotypes similar to craniosynostosis." (PMID 30336637, 2018). "In this study, especially the detected deregulation of TWIST1 expression, which was only detected in the patient iPSC-derived NPCs, may explain a large part of the patient phenotype (the craniosynostosis and the doubling of the thumbs)." (PMID 28126037, 2017). "These losses of contacts with several of its enhancers could lead to reduced TWIST1 expression in neural crest-derived cells involved in craniosynostosis and possibly contribute to the craniosynostosis phenotype." (PMID 28126037, 2017). "Moreover, in mice with TWIST1 haploinsufficiency, a model of syndromic craniosynostosis, overexpression of SPRY1 prevents suture fusion." (PMID 27606499, 2016). "Our main objective was to determine whether Twist1, FGFR1, FGFR2, or FGFR3 were the sites of causative mutation within our rabbit model of craniosynostosis." (PMID 23738319, 2013). "In conclusion, we sought to determine whether either FGFR1–FGFR3 or Twist1 was the locus of the defect resulting in our rabbit heritable model of craniosynostosis." (PMID 23738319, 2013). "In two different mouse models of craniosynostosis, the Twist1+/− heterozygous knockout (KO) and Mesp1Cre/Twist1+/F conditional heterozygous KO mice, we demonstrated that miR-200a was able to inhibit the premature suture closure and prevent craniosynostosis in these mice." (PMID 40845104, 2025). "However, the detailed mechanism of TWIST1 gene mutation causing craniosynostosis has not been fully elucidated." (PMID 38369459, 2024). "Given that maxillary hypoplasia is a common finding in patients with craniosynostosis, one might speculate that genetic variation in TWIST1 may also result in premature ossification of the maxillary sutures, resulting in a class III malocclusion due to maxillary hypoplasia." (PMID 36768894, 2023). "Additionally, some individuals with TWIST1 variants have isolated ptosis, without clinically apparent craniosynostosis." (PMID 35944701, 2022). "We show that asymmetric distribution of Erg and Six2 is lost in Twist1+/−;Tcf12+/− mutants, and in a companion study that similar asymmetric distribution of Grem1+ progenitors is lost in Tcf12−/− mutants, consistent with bones meeting end-on-end and fusing in these craniosynostosis models." (PMID 34376651, 2021).
craniosynostosis (continued). "In this manuscript we present data from mouse cross-breeding experiments designed to explore possible polygenic inheritance of craniosynostosis using Twist1/Igf1 and Twist1/Gsk3β compound heterozygotes to test hypotheses generated from our previous human expression data." (PMID 31442251, 2019). "Mutations in TWIST1 cause Saethre-Chotzen syndrome, a hereditary form of craniosynostosis, however, we have shown that disinhibition of RUNX2 caused by mutations in the highly conserved TWIST1 twist-box domain is associated with non-syndromic unilateral coronal and sagittal craniosynostosis." (PMID 31442251, 2019). "Therefore, we speculated that periostin may be involved in the development of cranial sutures in Twist1+/− mice and it could be a target for an adjuvant therapy to improve craniosynostosis." (PMID 29665811, 2018). "Therefore, we speculated that periostin may influence the biological behavior of suture-derived cells and ameliorate craniosynostosis in Twist1+/− mice." (PMID 29665811, 2018). "Although our samples were all derived from non‐syndromic craniosynostosis (NSC) patients to minimize genetic heterogeneity, we used the widely recognized Twist1+/− mouse model for in vivo validation." (PMID 41178597, 2026). "Overall, craniosynostosis affected 2 out of 42 patients in our cohort (5%), who both underwent direct sequencing of FGFR2, FGFR3, FGFR1 and TWIST1, with normal results." (PMID 29093661, 2017). "Our data show that the identified SNPs in FGFR1, FGFR2, and Twist1 all segregated independently of the craniosynostotic phenotype, and therefore a mutation within these genes is highly unlikely to be the causative agent of the craniosynostosis within our model." (PMID 23738319, 2013). "Exposure in utero to excess thyroxine, a thyroid hormone involved in numerous metabolic functions, failed to alter the severity or frequency of the craniosynostosis phenotype seen in Twist1+/− mice, although it slightly affected skull shape." (PMID 35451466, 2022). "The clinical hypothesis of craniosynostosis remained convincing and thus, molecular investigation of the FGFR3 and TWIST1 genes and array-CGH analysis to search for microdeletions/duplications were performed, all with negative results." (PMID 35885943, 2022). "The in vivo results demonstrated that periostin-treated Twist1+/− mice showed patent coronal sutures in comparison with non-treated Twist1+/− mice which have coronal craniosynostosis." (PMID 29665811, 2018). "Twist1 and Twist2 haploinsufficient mice did not present with premature ossification and craniosynostosis; instead they displayed reduced bone formation, impaired proliferation and differentiation of osteoprogenitors." (PMID 24971743, 2014). "Although no structural mutation within the coding sequence had been identified, we sought to more conclusively rule out the involvement of Twist1 within our rabbit model of craniosynostosis as well." (PMID 23738319, 2013). "The current study indicates that this rabbit model of nonsyndromic craniosynostosis likely does not devolve from any other mutation outside of the FGFR2 coding region and extends this same conclusion to FGFR1 and Twist1." (PMID 23738319, 2013). "Importantly, zebrafish mutants for established craniosynostosis genes (i.e., FGFR345 and TWIST1 and TCF1246) also displayed abnormal cranial bone growth and eventual ectopic sutures, which reinforce a plausible role of the prioritized genes in the disease pathogenesis." (PMID 37402774, 2023). "TWIST-1 expression and function have been correlated with the epigenetic regulator Enhance of Zeste Homolog 2 (EZH2) in mediating SCS cranial bone cell growth and differentiation, where Ezh2 knockdown in the mesenchymal lineage leads to craniosynostosis and other skeletal deformities." (PMID 33298158, 2020).
craniosynostosis (continued). "Lastly, in order to determine whether aberrant regulation of genes known to be involved in the aetiology of craniosynostosis underpinned any of the defects we observed, we examined the expression of Noggin, FGFR1/pFGFR1, FGFR2, Runx2 and Twist1 by immunohistochemistry." (PMID 27756203, 2016). "For example, in mouse models of Twist1+/− craniosynostosis, the earliest detectable defect is the aberrant expression of Notch2, which is a marker of osteogenesis, and it is abnormally expressed in non-osteogenic suture mesenchymal regions in Twist1+/− mouse embryos at E12.5." (PMID 35451466, 2022). "As reduced expression of TWIST1 could also be caused by mutation of non‐coding regulatory elements, we set out to screen the entire gene in SCS cases who were negative for known causes of craniosynostosis." (PMID 30040876, 2018). "To date, we have tested, by dideoxy‐sequencing of TCF12, 105 Dutch syndromic and nonsyndromic coronal craniosynostosis index patients with negative results for FGFR2, FGFR3, and TWIST1 testing." (PMID 27158814, 2016).
Saethre-Chotzen syndrome (57 papers, 2007 to 2025). "Twist1 functions to coordinate the activities of the BMP and RTK pathways, and, in humans, TWIST1 haploinsufficiency causes Saethre-Chotzen syndrome." (PMID 40845104, 2025). "The deletion included, among others, the disease-associated gene TWIST1, which has been associated with several allelic disorders, including Saethre-Chotzen syndrome." (PMID 40225364, 2025). "Consistent with this, TWIST1 is a transcription factor critical for specification of the cranial mesoderm, and heterozygous LOFs in the gene are associated with Saethre-Chotzen syndrome, a disorder characterized by congenital skull and limb abnormalities." (PMID 37292653, 2024). "When the gene Twist1 that is mutated in Saethre-Chotzen syndrome is knocked out in Ctsk-lineage cells, it recapitulates the signature craniosynostoiss phenotype associated with Twist1 loss." (PMID 38442300, 2024). "Direct interactions of HAND2 with TWIST1 are essential for limb bud development, as their altered dimerization causes Saethre-Chotzen syndrome with associated distal limb skeletal malformations." (PMID 37414772, 2023). "Heterozygous mutation of transcription factor 12 (TCF12), like that of TWIST1, can lead to the development of Saethre-Chotzen syndrome." (PMID 35451466, 2022). "Saethre-Chotzen syndrome, defined by TWIST1 loss-of-function mutation, is the second most prevalent form of syndromic COR craniosynostosis." (PMID 34330896, 2021). "The loss of Twist1 in the suture mesenchyme also causes cell lineage mixing and coronal suture fusion in the Twist1+/− mouse model of Saethre-Chotzen syndrome." (PMID 32916911, 2020). "Saethre-Chotzen syndrome (OMIM # 101400) is caused by TWIST1 mutations, and it is an autosomal dominant craniosynostosis syndrome with uni- or bi-lateral coronal synostosis and mild limb deformities (Musculoskeletal Diseases)." (PMID 32011235, 2020). "Mutations in TWIST1 are associated with Saethre-Chotzen syndrome (SCS), a rare congenital disorder characterized with osteogenesis abnormalities." (PMID 32051525, 2020). "Mutations in the TWIST1 gene in human is associated with craniosynostosis (premature closure of the sutures between the bones of the skull), as noted in the Saethre-Chotzen syndrome-affected individuals." (PMID 32655411, 2020). "The most common form of syndromic coronal synostosis is Saethre-Chotzen syndrome, which is caused by heterozygous loss-of-function mutations in TWIST1 or TCF12." (PMID 31869306, 2019). "Accordingly, haploinsufficiency of TWIST1 can cause limb and craniofacial malformations as part of Saethre-Chotzen syndrome." (PMID 30372441, 2018). "In humans, TWIST1 mutations are associated with Saethre-Chotzen syndrome, an autosomal dominant craniosynostosis disorder that also exhibits distal limb malformation, such as PPD." (PMID 30372441, 2018). "TWIST1 haploinsufficiency can cause limb and craniofacial malformations, such as Saethre-Chotzen syndrome." (PMID 30372441, 2018). "Mutation of Twist1 in humans leads to Saethre-Chotzen syndrome, a disease of autosomal dominant inheritance characterized by manifestations such as craniosynostosis, ptosis, and hypertelorism." (PMID 28099910, 2017). "The TWIST1 gene is involved in morphogenetics, and deletions are known to cause Saethre-Chotzen syndrome." (PMID 28814329, 2017). "Mutations in human Twist1 lead to the Saethre-Chotzen syndrome, which is associated with severe abnormalities in fusion of the cranial bones and digit defects." (PMID 26361389, 2015). "Of these three mutants, Twist1 R116W, Twist1 R118H, and Twist1 R120A, the former two are associated with the congenital disorder Saethre-Chotzen Syndrome, and all are predicted to have impaired DNA binding capabilities." (PMID 23555309, 2013). "As reported in the human Saethre-Chotzen syndrome, there is a marked phenotypic variability (including horn development) among individuals carrying the same TWIST1 mutation." (PMID 21814570, 2011).
Saethre-Chotzen syndrome (continued). "Within this region, the TWIST1 gene encoding a transcription factor was considered as a strong candidate gene since its haploinsufficiency is responsible for the human Saethre-Chotzen syndrome, characterized by skull coronal suture synostosis." (PMID 21814570, 2011). "Mutations Twist1 have been found in patients with Saethre-Chotzen syndrome which is associated with digit malformation." (PMID 21054883, 2010). "Mutations in TWIST1 result in Saethre-Chotzen Syndrome (MIM #101400, SCS), known as an autosomal dominant craniosynostosis." (PMID 19534813, 2009). "In addition, variants present in the bHLH domain of TWIST1 have been reported to cause Saethre-Chotzen syndrome." (PMID 40287710, 2025). "TWIST1 heterozygous loss of function mutations cause Saethre-Chotzen syndrome." (PMID 40845104, 2025). "TWIST1 haploinsufficiency is a common defect in CS associated with Saethre-Chotzen syndrome." (PMID 38357924, 2024). "Such CV malformations were also observed in a more profound mouse model of Saethre-Chotzen syndrome, in which one Twist1 allele possesses a loss-of-function mutation and the other Twist1 allele is deleted in the periosteal dura and sutures (known as Twist1fl/–;Sm22a-Cre mice)." (PMID 38357924, 2024). "Heterozygous loss-of-function mutations in TWIST1 lead to Saethre-Chotzen syndrome in humans." (PMID 35451466, 2022). "The function of TWIST1 in osteogenesis has been reflected by the identification of the TWIST1 mutations in Saethre-Chotzen syndrome (SCS), a rare congenital disorder often associated with cone-shaped head, asymmetrical face, hand and foot malformation, and even mental retardation." (PMID 32051525, 2020). "Moreover, mutations in TWIST1 found in Saethre-Chotzen Syndrome that prevent its dimerization and nuclear translocation have been shown to lead to degradation of the protein." (PMID 28283022, 2017). "Deletions of TWIST1 cause Saethre-Chotzen syndrome (SCS; OMIM 101400)." (PMID 28814329, 2017). "In humans, Twist1 malfunction was first linked to Saethre-Chotzen syndrome and later identified to play an essential role in tumor initiation, stemness, angiogenesis, invasion, metastasis, and chemo-resistance in a variety of carcinomas, sarcomas, and hematological malignances." (PMID 28099910, 2017). "Indeed, more than 80 mutations in the TWIST1 gene have been reported in humans as the cause of skull coronal suture synostosis, a symptom of the Saethre-Chotzen syndrome." (PMID 21814570, 2011). "Therefore, our Twist1-F191S mutant mouse could be an additional and valuable model to study disease mechanisms underlying Saethre-Chotzen syndrome caused by dysfunction of TWIST1." (PMID 32051525, 2020). "Some loss-of-function mutations of the TWIST1 gene have been shown to cause an autosomal dominant craniosynostosis, known as the Saethre-Chotzen syndrome (SCS)." (PMID 28521820, 2017). "The majority of patients with Saethre-Chotzen syndrome (SCS) present loss-of-function mutations in transcription factor TWIST1 which is thought to negatively regulate FGFR1, 2 and 3 and the osteogenic transcription factor Runx2." (PMID 20108486, 2009). "Along the same lines, loss-of-function mutations in TWIST1, which directly antagonizes RUNX2 in the developing coronal suture, cause Saethre-Chotzen syndrome, characterized by coronal craniosynostosis." (PMID 40087503, 2025). "Premature fusion of cranial sutures is most often associated with Apert syndrome (FGFR2), Muenke syndrome (FGFR3), Crouzon syndrome (FGFR2), Pfeiffer syndrome (FGFR2, FGFR1), and Saethre-Chotzen syndrome (TWIST1)." (PMID 37629737, 2023). "For example, patients that are haploinsufficient for TWIST1 develop Saethre-Chotzen syndrome, but display substantial phenotypic heterogeneity." (PMID 35451466, 2022).